FMO3 (flavin containing dimethylaniline monoxygenase 3)
Diseases named in the same sentence as FMO3 in open-access papers (continued):
Sharing a sentence is not in itself a finding about the gene and the disease.
diabetes (10 papers, 2009 to 2024). "Several potential mechanisms by which the FMO3 pathway associates with AS have been identified, including alterations in cholesterol and lipid metabolism, Glu metabolism, diabetes-related traits, and vascular inflammation." (PMID 35433899, 2022). "Because Fmo3 KO exerted a protective role against β-cell dysfunction, we examined the possibility of implementing Fmo3 as a therapeutic target to treat diabetes." (PMID 38514666, 2024). "Inhibition of pJNK1 decreases diabetes-induced serum NO levels, Fmo3 and ICAM expression in the liver, IL-1β production in Kupffer cells, and ICAM expression in the aorta." (PMID 29851956, 2018). "Diabetes induced a significant increase in Fmo3 expression in the liver of STZ-DM mice compared with that in the control group." (PMID 29851956, 2018). "Increased Fmo3 expression in the liver is closely related to metabolic syndrome and cholestasis in diabetes." (PMID 29851956, 2018). "In conclusion, this study showed that diabetes induces Fmo3 and ICAM expression and possible vascular impairment through enteric dysbiosis-related JNK pathways." (PMID 29851956, 2018). "The effect and the regulatory mechanism of intestinal microflora on diabetes-induced Fmo3 and intercellular adhesion molecule (ICAM) expression were examined in streptozotocin-induced diabetic mice (STZDM) and Akita mice (C57BL/6J-Ins2Akita)." (PMID 29851956, 2018). "The findings of the present study suggest that diabetes induced Fmo3 and ICAM expression and possible vascular impairment through enteric dysbiosis-related JNK pathways in the host." (PMID 29851956, 2018). "Our data suggest that diabetes induces enteric dysbiosis, Fmo3 expression in the liver, and ICAM expression in the aorta." (PMID 29851956, 2018). "Our data suggest that enteric dysbiosis-induced reduction of ROS production and increase in iNOS and NO production play an important role in diabetes-induced activation of Kupffer cells and Fmo3 and ICAM expression in the liver." (PMID 29851956, 2018). "Altogether, these results suggest that the intestinal microbiota play an important role in diabetes-induced Fmo3 expression in the liver and ICAM expression in the liver and aorta." (PMID 29851956, 2018). "In conclusion, diabetes induced the expression of both Fmo3 and ICAM expression and possible vascular impairment through enteric dysbiosis." (PMID 29851956, 2018). "The role of pJNK1 in diabetes-induced Fmo3 expression in the liver was assessed by analyzing Fmo3 expression in the liver of Ins2Akita-JNK1-/- mice." (PMID 29851956, 2018). "Some studies suggest Fmo3 plays a role in metabolic diseases including diabetes." (PMID 37609485, 2023). "Many studies have linked Fmo3 and TMAO to diabetes-related cardiovascular disease, while others have reported that the effects of Fmo3 are unrelated to TMA or TMAO metabolism or that Fmo3 expression and function may be related to acetaminophen-induced effects." (PMID 37958806, 2023). "The third objective was to determine whether JNK inhibition could decrease NO production and diabetes-induced Fmo3 and ICAM expression." (PMID 29851956, 2018). "Diabetes decreases Lactobacillus growth and ROS levels in the intestine and induces iNOS and pJNK protein expression in the intestine, serum NO levels, activation of Kupffer cells, and Fmo3 and ICAM expression in the liver." (PMID 29851956, 2018). "Moreover, FOS or dead L. plantarum feeding significantly decreased the diabetes-induced Fmo3 and ICAM expression in STZ-induced diabetic and Ins2Akita mice." (PMID 29851956, 2018). "Reversal of diabetes-induced enteric dysbiosis with prebiotic or probiotic feeding could decrease pJNK and iNOS expression in the intestinal mucosa, serum NO levels, and Fmo3 and ICAM expression in the liver and aorta in diabetic patients." (PMID 29851956, 2018). "Diabetes-induced Fmo3 and ICAM expression could be reversed by pJNK inhibition or by correcting enteric dysbiosis." (PMID 29851956, 2018).
diabetes (continued). "The effect of diabetes on Fmo3 expression in the liver was assessed by examining Fmo3 mRNA expression in the liver using real-time PCR in STZ-DM mice." (PMID 29851956, 2018). "Reversal of enteric dysbiosis with FOS or dead L. plantarum feeding increases ROS production in the intestine and decreases iNOS expression, NO production, Fmo3 expression and ICAM expression in diabetes." (PMID 29851956, 2018). "We next examined the mechanism of enteric dysbiosis-induced Fmo3 and ICAM expression in diabetes." (PMID 29851956, 2018). "Thus, higher Fmo3 and gut microbiota levels could explain the elevation of the TMAO concentration in diabetes." (PMID 38514666, 2024). "In addition, the injection of nondiabetic plasma-treated SVFs not only repressed the expression of the diabetes-induced ICAM, FMO3, IL-6, IL-1β, iNOS, TNF-α, and DPP4 expression, but also suppressed the phosphorylation of JNK and NF-κB in the liver of diabetic mice." (PMID 35883204, 2022). "Reversal of diabetes-induced enteric dysbiosis by prebiotic (FOS) or probiotic (dead L. plantarum) treatment decreased diabetes-induced pJNK and iNOS expression in the intestine, Fmo3 expression in the liver, IL-1β expression in Kupffer cells, and ICAM expression in the aorta and liver." (PMID 29851956, 2018).
Hypertension (5 papers, 2005 to 2025). The presence of chronic increased pressure in the systemic arterial system. "The rs2266782 variant of the FMO3 gene was linked to a higher incidence of hypertension among smokers in a Russian population." (PMID 41035740, 2025). "The FMO3 variant Glu158Lys, also Glu308Gly, was linked to the susceptibility to hypertension-related cerebrovascular disease in Turks." (PMID 41035740, 2025). "A single study investigated the relationship between common polymorphisms of the FMO3 gene and hypertension in Irish population." (PMID 25243081, 2014). "This is the first study reporting the association of the FMO3 gene polymorphism and the risk of essential hypertension." (PMID 25243081, 2014). "The present study demonstrated for the first time that the FMO3 gene polymorphism is associated with susceptibility to essential hypertension, the result which was originally found in Kursk population and then validated in an independent population from Belgorod region." (PMID 25243081, 2014). "The present study was designed to investigate whether common functional polymorphism E158K (rs2266782) of the FMO3 gene is associated with susceptibility to essential hypertension in Russia." (PMID 25243081, 2014). "The recessive disorder trimethylaminuria is caused by defects in the FMO3 gene, and may be associated with hypertension." (PMID 16324215, 2005). "As high levels of circulating catecholamines contribute to hypertension, it is proposed that polymorphisms of FMO3 gene could contribute to impaired catecholamine metabolism and hypertension." (PMID 16324215, 2005). "Herein we report our investigations into a possible association of haplotypes of three polymorphic variants of the FMO3 gene with the phenotype of blood pressure in an occupational Irish adult population and with presence of essential hypertension in an Irish cardiovascular disease (CVD) population." (PMID 16324215, 2005). "We investigated whether common polymorphisms of the FMO3 gene confer an increased risk for elevated blood pressure and/or essential hypertension." (PMID 16324215, 2005). "Many low frequency and rare variants have been cited to cause trimethylaminuria in studies of families with the condition, prompting the exploration of the hypothesis that rare and low frequency variants (MAF < 5%) in the exome sequence of FMO3 are associated with hypertension." (PMID 30906589, 2019). "While null alleles in the FMO3 gene may be too rare to cause any appreciable effect on the population burden of hypertension, prevalent polymorphisms with documented in vitro evidence of variation in catecholamine metabolism may however potentially associate with and predispose to this condition." (PMID 16324215, 2005). "We hypothesised that common FMO3 polymorphisms might predispose to essential hypertension." (PMID 16324215, 2005). "Gene encoding flavin-containing monooxygenase 3 (FMO3), a microsomal antioxidant defense enzyme, has been suggested to contribute to essential hypertension (EH)." (PMID 25243081, 2014). "We also observed in the Kursk population that the increased risk of hypertension in carriers of heterozygous genotype 158KK of the FMO3 gene occurs only in smokers, whereas nonsmokers possessing this genotype do not have the risk of the disease." (PMID 25243081, 2014). "However, these researchers found that none of the FMO3 gene polymorphisms was associated with hypertension risk." (PMID 25243081, 2014). "FMO3 genotypes (E158K, V257M, E308G) were determined in 387 healthy subjects with ambulatory systolic and diastolic blood pressure measurements, and in a cardiovascular disease population of 1649 individuals, 691(41.9%) of whom had a history of hypertension requiring drug treatment." (PMID 16324215, 2005).
metabolic syndrome (5 papers, 2018 to 2022). A cluster of metabolic risk factors for CARDIOVASCULAR DISEASES and TYPE 2 DIABETES MELLITUS. "Furthermore, FMO3 may promote dyslipidemia by regulating multiple genes involved in hepatic lipogenesis and gluconeogenesis." (PMID 30347638, 2018).
cholestasis (3 papers, 2018 to 2025). Impairment of the bile flow caused by obstruction within the liver, or outside the liver in the bile duct system. "Cancer and/or non-alcoholicfatty liver disease-related cirrhosis showed larger deteriorationin levels of CYP3A4, 2C8, 2E1, 1A6, UGT2B4/7, CES1, FMO3/5, EPHX1,MGST1/3, BSEP, and OATP2B1 than the cholestasis set." (PMID 34428046, 2021). "The volatile TMA crosses the intestinal barrier, is transported by the portal vein, and reaches the liver, where it is oxidized to TMAO by flavin-containing monooxygenase 3 (FMO3) and FMO1, two microsomal cytochromes whose transcription is modulated by bile acids and upregulated by cholestasis." (PMID 40427399, 2025).
hepatoma (3 papers, 2006 to 2022). "We found that the expression level of CHRNA4 and nicotine metabolism genes, including CYP2A6, FMO3, UGT2B7 were dramatically down-regulated in human hepatocellular carcinoma, suggesting disrupted nicotine metabolism in hepatocellular carcinoma." (PMID 28583088, 2017).
chronic kidney disease (2 papers, 2022 to 2023). Impairment of the renal function secondary to chronic kidney damage persisting for three or more months. "Although there is past literature linking TMAO to urea cycle, this is the first published work showing that FMO3 and CPS1 may directly interact, implicating a role for FMO3 in chronic kidney disease irrespective of TMAO formation." (PMID 35202247, 2022).
Cognitive impairment (2 papers, 2020 to 2024). Abnormal cognition is characterized by deficits in thinking, reasoning, or remembering. "Development of novel therapeutics targeting TMAO, especially the enzyme FMO3 through specific inhibition could help in attenuating the cognitive deficits seen in AD and other diseases with cognitive impairment." (PMID 32903435, 2020). "Indeed, the FMO3 inhibitor employed in this study, DIM, is already available as nutritional supplements, which may have a great deal of promise for preventing cognitive impairment induced by sleep loss." (PMID 39669439, 2024). "In contrast, FMO3 inhibitor 3,3′-diindolylmethane (DIM) alleviates SD-induced cognitive impairment by targeting the liver–brain axis." (PMID 39669439, 2024).
gallstones (2 papers, 2021). Solid crystalline precipitates in the biliary tract, usually formed in the gallbladder, resulting in the condition of cholelithiasis. "The FMO3 protein encoded by Fmo3 (the most upregulated mRNA) is found associated with gallstone formation in mice." (PMID 35127549, 2021). "FMO3 loss or gain-of-function experiments in cholesterol fed mice demonstrated that TMAO induces ABCG5 and ABCG8 expression, and presumably increases bile cholesterol content to drive gallstone formation." (PMID 34445033, 2021). "Since TMAO reduction by FMO3 knockout decreased bile cholesterol content, elevated TMAO presumably drives gallstone formation." (PMID 34445033, 2021).
Glucose intolerance (2 papers, 2022 to 2024). Glucose intolerance (GI) can be defined as dysglycemia that comprises both prediabetes and diabetes. "Collectively, these data showed that Fmo3 deficiency in choline-fed mice improved islet morphology, β-cell function and glucose intolerance." (PMID 38514666, 2024). "The intravenous glucose tolerance test (IVGTT) showed that Fmo3-ASO markedly improved glucose intolerance in db/db mice." (PMID 38514666, 2024). "Together, these data suggest that the genetic deficiency of Fmo3 does not significantly alter metabolic hormone levels, but when exposed to TCDD, male Fmo3−/− mice exhibit marked glucose intolerance compared to TCDD-treated Fmo3+/+ controls." (PMID 35448550, 2022). "Furthermore, we demonstrated that TMAO directly decreases GSIS in human primary islets and that antisense Fmo3 improved β-cell function and glucose intolerance in db/db mice." (PMID 38514666, 2024). "Furthermore, IPGTT and ITT experiments indicated that Fmo3 knockdown improved fasting blood glucose, glucose intolerance, and insulin sensitivity in db/db mice." (PMID 38514666, 2024). "Interestingly, we found that TCDD-treated Fmo3−/− mice display clear glucose intolerance compared to TCDD-treated Fmo3+/+ mice." (PMID 35448550, 2022).
Hepatic steatosis (2 papers, 2021). Steatosis is a term used to denote lipid accumulation within hepatocytes. "This complex interaction between sex hormones, GH signaling and liver steatosis may converge on Cux2 contributing to the perturbation of sex-biased gene expression, such as that of Fmo3 and Acot3, in all four mice models of NAFLD tested herein." (PMID 34576136, 2021). "As the generation of TMAO depends on oxidation by hepatic flavin-containing monooxygenase (FMO3), the improved hepatic steatosis seen after RYGB surgery might result in restored hepatic function and FMO3 activation." (PMID 35046891, 2021).
liver disease (2 papers, 2021 to 2022). "FMO3 protein and its metabolite (TMAO) participate in the TAF–FMO3–TMAO pathway, which could regulate lipid metabolism, while the downregulated mRNA Dmbt1 could encode the DMBT1 protein, which is related to liver injury and repair mechanisms in liver diseases." (PMID 35127549, 2021). "Interestingly, mRNA levels for FMO3 are uniquely repressed in patients with more severe AH (AH with liver failure [MELD 22–28] and AH with emergency liver transplant [MELD 18–21]), but not in other liver disease etiologies such as non-alcoholic fatty liver disease (NAFLD) or viral hepatitis." (PMID 35084335, 2022).
liver failure (2 papers, 2022). A liver disease characterized by the liver losing or has lost all of its function. "Our study revealed that PEMF treatment promoted the expression of Fmo3 in the liver of LPS-induced septic shock mice, which suggests that PEMF treatment prevented liver failure by up-regulating expression of the Fmo3 gene." (PMID 35628471, 2022).
nicotine dependence (2 papers, 2017 to 2020). Physical and psychological dependence on nicotine. "Recent publications have shown that N-oxidation of nicotine mediated by FMO1 and FMO3 occurs in the brain, and, moreover, that functional variation in FMO3 (rs2266780, E308G) is associated with nicotine dependence." (PMID 33363564, 2020). "Specifically, we focused on the two genomic segments including FMO1,FMO3, and pseudo gene FMO6P, and aimed to investigate the potential association between FMO genes and nicotine dependence." (PMID 28413702, 2017). "Specifically, we focused on the two genomic segments including FMO1, FMO3 (protein coding genes for FMO 1 and 3), and FMO6P (pseudo gene), and aimed to investigate the potential association between FMO genes and nicotine dependence." (PMID 28413702, 2017). "Although a recent study has shown that common polymorphisms in FMO3 can influence nicotine clearance, no study has provided direct evidence of the association between FMO3 polymorphisms and nicotine dependence." (PMID 28413702, 2017). "In summary, we tested the genetic effects of three FMOs genes (FMO1, FMO3, and FMO6P) on nicotine dependence by performing targeted sequencing on 2,852 nicotine‐dependent and nondependent smokers." (PMID 28413702, 2017). "On the other hand, if the signal we identified in FMO6P is not the surrogate for effects of SNPs in FMO3, but has an independent effect on nicotine dependence, then further research will be needed to clarify the underlying function of FMO6P." (PMID 28413702, 2017).
Sepsis (2 papers, 2022 to 2025). Sepsis is defined as life-threatening organ dysfunction caused by a dysregulated host response to infection. "Notably, flavin-containing monooxygenase 3 (Fmo3), the enzyme responsible for TMAO production in the liver, was reduced in sepsis-associated AKI." (PMID 40821837, 2025). "In this regard, the evaluation of NADP metabolism in the liver by determining Fmo3 expression might be a biomarker for sepsis." (PMID 35628471, 2022).
albinism (1 paper, 2020). A congenital disorder characterized by partial or complete absence of melanin pigment in the eyes, hair, or skin. "Cas9 targeting of FMO3 resulted in the same phenotype of albinism in larvae and these larvae were screened and selected based on lack of larval pigment." (PMID 32029769, 2020).
androgenetic alopecia (1 paper, 2022). "Finasteride, which originally aimed to treat prostate hyperplasia and androgenetic alopecia, could reduce TMAO level in HFD-fed mice by inhibiting the FMO3, a key enzyme involved in the process of TMA-to-TMAO conversion." (PMID 36045744, 2022).
cerebrovascular diseases (1 paper, 2024). "TMA, which is oxidized by flavin-containing monooxygenase 3 (Fmo3) to trimethylamine N-oxide (TMAO), is a key risk factor for cardiovascular and cerebrovascular diseases." (PMID 39135557, 2024).
chronic heart failure (1 paper, 2025). "One study indicated that the SNP rs2266782 in the FMO3 gene affects outcomes in chronic heart failure patients by altering plasma TMAO concentrations, with the AA genotype linked to reduced TMAO levels." (PMID 41035740, 2025).
clonorchiasis (1 paper, 2021). Infection of the biliary passages with clonorchis sinensis, also called Opisthorchis sinensis. "Therefore, we speculate that mRNA Fmo3 and Dmbt1 might contribute to lipid metabolism and liver injury in clonorchiasis." (PMID 35127549, 2021).
COVID-19 (1 paper, 2023). A disease caused by infection with severe acute respiratory syndrome coronavirus 2. "Furthermore, other organs such as normal human heart, COVID-19 heart and lung, immune cell from human lung tumor, mouse glomerulus diseases, and aging mouse brain can express FMO3 in different cell types and can also express other FMOs family members." (PMID 36394956, 2023).
endometriosis (1 paper, 2023). The growth of functional endometrial tissue in anatomic sites outside the uterine body. "In our previous whole-genome expression microarray analysis, we identified that FMO3 was also more specific for the fallopian tube and endometriosis, but not for the endometrium, although the relationship between FOLR1 and FMO3 is unclear." (PMID 36936232, 2023).
glucose metabolic disorders (1 paper, 2020). "Our results showed that the overexpression of FMO3 ameliorated lipid and glucose metabolic disorders in the aging model to the same extent as CR." (PMID 31927537, 2020).
Hypercholesterolemia (1 paper, 2015). An increased concentration of cholesterol in the blood. "In the presence of the Paigen diet, LIRKO mice developed severe hypercholesterolemia that was entirely prevented by the knockdown of FMO3." (PMID 25849138, 2015).